SUPV3L1 (Suv3 like RNA helicase)
Description:
Major helicase player in mitochondrial RNA metabolism. Component of the mitochondrial degradosome (mtEXO) complex, that degrades 3' overhang double-stranded RNA with a 3'-to-5' directionality in an ATP-dependent manner. Involved in the degradation of non-coding mitochondrial transcripts (MT-ncRNA) and tRNA-like molecules. ATPase and ATP-dependent multisubstrate helicase, able to unwind double-stranded (ds) DNA and RNA, and RNA/DNA heteroduplexes in the 5'-to-3' direction. Plays a role in the RNA surveillance system in mitochondria; regulates the stability of mature mRNAs, the removal of aberrantly formed mRNAs and the rapid degradation of non coding processing intermediates. Also implicated in recombination and chromatin maintenance pathways. May protect cells from apoptosis. Associates with mitochondrial DNA.
Synonyms: SUV3
Tractability: Small molecule: a structure with a bound ligand is known; it has a high-quality binding pocket. PROTAC: ubiquitination databases record sites on it; its protein half-life has been measured.
Target class: Enzyme
Gene: Protein-coding gene on chromosome 10 (69,180,234 to 69,209,108, forward strand). Ensembl gene ENSG00000156502.
Subcellular location: Nucleus; Mitochondrion matrix; Mitochondrion matrix, mitochondrion nucleoid
Subcellular location (Human Protein Atlas): Mitochondria
Pathways (Reactome):
Metabolism of RNA: Mitochondrial RNA degradation
Gene Ontology:
Molecular function: 3'-5' RNA helicase activity; 3'-5'-RNA exonuclease activity; ATP hydrolysis activity; DNA binding; DNA helicase activity; double-stranded RNA binding; identical protein binding; protein binding; protein homodimerization activity; RNA binding; RNA helicase activity; helicase activity; ATP binding
Biological process: DNA recombination; mitochondrial mRNA catabolic process; mitochondrial mRNA surveillance; mitochondrial ncRNA surveillance; mitochondrial RNA 3'-end processing; mitochondrial RNA catabolic process; mitochondrial RNA surveillance; mitochondrion organization; negative regulation of apoptotic process; positive regulation of cell growth; positive regulation of mitochondrial RNA catabolic process; RNA catabolic process
Cellular component: mitochondrial degradosome; mitochondrial matrix; mitochondrial nucleoid; mitochondrion; nucleus
Genetic constraint (gnomAD): Loss-of-function variants: 29 observed, 67.32 expected, observed/expected ratio (o/e) 0.43, 90% interval 0.32 to 0.59. The upper end of that interval is the gene's LOEUF score, 0.59, which puts it in group 2 of 6, group 1 being the genes least tolerant of losing a copy. Missense variants: 756 observed, 978.07 expected, observed/expected ratio (o/e) 0.77, 90% interval 0.73 to 0.82. Synonymous variants: 356 observed, 354.59 expected, observed/expected ratio (o/e) 1, 90% interval 0.92 to 1.1.
Homologues: Orthologues: chimpanzee SUPV3L1 (99% identical), macaque SUPV3L1 (98% identical), dog SUPV3L1 (91% identical), rabbit SUPV3L1 (91% identical), guinea pig SUPV3L1 (88% identical), rat Supv3l1 (88% identical), mouse Supv3l1 (88% identical), pig SUPV3L1 (87% identical), tropical clawed frog supv3l1 (68% identical), zebrafish supv3l1 (66% identical), Drosophila melanogaster Suv3 (55% identical), Caenorhabditis elegans C08F8.2 (42% identical).
Diseases named in the same sentence as SUPV3L1 in open-access papers:
SUPV3L1 is named in the same sentence as 15 diseases in open-access papers, as found by Europe PMC text mining. Sharing a sentence is not in itself a finding about the gene and the disease. The quoted sentences say what the papers report.
Ataxia (1 paper, 2024). Ataxia refers to impaired coordination of voluntary muscle movement. "The patient’s phenotype, characterized by neurological symptoms such as ataxia, spasticity, as well as optic atrophy, and skin abnormalities, aligns with previous reports but also extends the clinical variability of SUPV3L1-associated disorders." (PMID 39596606, 2024). "SUPV3L1-associated disorders seem to exhibit a variable spectrum of presentations, including neurodevelopmental disorders, ataxia, white matter lesions, skin hypopigmentation, and visual defects." (PMID 39596606, 2024).
gastric cancer (1 paper, 2020). A primary or metastatic malignant neoplasm involving the stomach. "It was found that expression of SLC22A17 (HR = 1.58 (1.18–2.12), P = 0.0022) was associated with worse overall survival (OS) for gastric cancer patients,expression of SUPV3L1 (HR = 0.6 (0.45–0.8) P = 0.00034) was associated with good overall survival (OS) for gastric cancer patients." (PMID 32164594, 2020).
prostate carcinoma (1 paper, 2018). A carcinoma that arises from epithelial cells of the prostate gland. "Five genes CGNL1, SUPV3L1, TATDN2, CASKIN1, and GOLGA7B are of unknown functions in either prostate cancer tumorigenesis or tumorigenesis in general." (PMID 30024105, 2018).
sarcopenia (1 paper, 2024). Progressive decline in muscle mass due to aging which results in decreased functional capacity of muscles. "Mice with a conditional knockout of Supv3L1 display premature aging phenotypes, including sarcopenia, loss of adipose tissue, and skin abnormalities, underscoring its role in maintaining mitochondrial function and overall cellular homeostasis." (PMID 39596606, 2024).
tumor (5 papers, 2015 to 2023). "There was a significant difference (P < 0.05) in tumor mutational burden between patients in the high and low group, high expression of SUPV3L1 and infiltration of Th2 cells and T helper cells and low expression of SLC22A17 and infiltration of Mast cells coupled with a high mutational burden." (PMID 32164594, 2020).
Digestive system tumor (1 paper, 2020). "Digestive system tumor compared with paracancer, there was a significant difference (P < 0.05) in the expression of SUPV3L1 and SLC22A17." (PMID 32164594, 2020).
mitochondrial disease (1 paper, 2024). "This case reinforces the importance of considering SUPV3L1 mutations in the differential diagnosis of mitochondrial diseases, particularly those presenting with neurodevelopmental issues and skin pigmentation abnormalities." (PMID 39596606, 2024). "A nonsense homozygous variant in the SUPV3L1 gene was recently associated with mitochondrial disease." (PMID 39596606, 2024). "Our findings highlight the critical role of a second opinion and in-depth whole genome data analysis in undiagnosed mitochondrial disease cases, underscored by the identification of two compound heterozygous variants in the SUPV3L1 gene in a patient with a unique clinical presentation." (PMID 39596606, 2024).
SUPV3L1 also shares sentences with these, for which no sentence is quoted: Cushing syndrome (1 paper); dilated cardiomyopathy (1); epilepsy (1); malaria (1); neurodegenerative disease (1); neurodevelopmental disorder (1); optic atrophy (1); prediabetes (1).